POSTN (periostin)
Diseases named in the same sentence as POSTN in open-access papers (continued):
Sharing a sentence is not in itself a finding about the gene and the disease.
cancer (continued). "Notch1 associates with these RBPJ binding sites after activation in liver bile duct carcinoma cells, and this interaction may promote Notch1-mediated regulation of POSTN transcription, as the Notch1/RBPJ complex is known to control cell fate decisions, proliferation, and differentiation in cancer." (PMID 41018265, 2025). "Of particular interest, we found through enrichment analysis that signaling pathways such as PERIOSTIN, FGF and ANGPTL were highly enriched in Migrasomehighfibro cells, suggesting that these fibroblasts may affect cancer cell migration and invasion through mechanisms such as the PI3K/Akt pathway." (PMID 40443671, 2025). "Subsequently, gene enrichment analysis of POSTN was performed in the TCGA dataset and GSE31210 dataset, which indicated that POSTN may primarily promote cancer progression by participating in the occurrence of epithelial-mesenchymal transition (EMT) (P < 0.001)." (PMID 40991535, 2025). "In addition, to better understand the role of POSTN and PDPN in cancer development, similar to our previous work and that of other authors, it was performed an analysis of the correlation of the expression of these two proteins with the expression of the Ki67 antigen." (PMID 41361308, 2025). "POSTN plays important roles in various processes of tumorigenesis and metastasis, including the induction of epithelial–mesenchymal transition (EMT), enhancement of Akt and Erk activity in cancer stem cells, and involvement of the PI3K/Akt/survivin pathway in POSTN-mediated chemotherapy resistance." (PMID 39272982, 2024). "Furthermore, the relationship between the level of POSTN expression and the presence of factors that promote blood-vessel formation (e.g., the VEGF protein family) has already been described in many types of cancer." (PMID 39272978, 2024). "Additionally, the levels of periostin, connective tissue growth factor (CTGF), and plasma cuprocyanin, all of which have significant roles in cancer progression, were elevated in these mice, as was that of serpinA3 protein, which promotes colorectal cancer development." (PMID 39634266, 2024). "POSTN plays important roles in various processes of tumorigenesis and metastasis, including induction of epithelial–mesenchymal transition (EMT), enhancement of Akt and Erk activity in cancer stem cells, and involvement of the PI3K/Akt/survivin pathway in POSTN-mediated chemotherapy resistance." (PMID 39272982, 2024). "Some recent studies have reported the expression of these genes (e.g., POSTN, APOE) in subsets of ESCC fibroblasts and macrophages, suggesting the existence of these subsets in ESCC microenvironment, but their role in how they interact with cancer cells or immune cells are largely unexplored." (PMID 36709495, 2023). "CTHRC1 secretion in the cancer cell lines was not influenced by periostin treatment either." (PMID 37444482, 2023). "However, the effects of elevated exogenous levels of periostin in cancers, such as those in the tissue microenvironment, have not been extensively investigated." (PMID 38049490, 2023). "In addition to their role in ECM construction, myCAFs may also enhance the stemness and proliferation of cancer cells by overexpressing secreted factors, including SEMA3C, POSTN, and CXCL6." (PMID 35986392, 2022). "Periostin expression and its role in cancer progression in UTUCs have not yet been reported." (PMID 35850759, 2022). "Given the altered expression of periostin in acute IBD and during remission in human patients, and the link to cancer progression in general as well as in CRC in mouse models, it is tempting to speculate that periostin may likely play a similar role in CRC in human patients." (PMID 34512647, 2021). "Therefore, PN1 and PN3, which include exon 17, may be cleaved to diversify the protein’s function, and the low molecular weight POSTN protein fragment which includes exon 17, accumulates in the ECM of cancer cells." (PMID 33919736, 2021).
cancer (continued). "As a result, the secreted POSTN short fragment of approximately 40 kDa which contains exon 17 but not exon 12, may be transported to cancer cells, whereas the POSTN fragment of approximately 75 kDa which contains exon 12 may remain in the stroma." (PMID 33919736, 2021). "In addition, the results of our studies tackle for the first time the subject of POSTN expression on the mRNA level in the microdissected stromal cells (CAFs) compared to cancer cells and non-malignant lung cells." (PMID 32987711, 2020). "This complicates the use of the protein itself as a biomarker for cancer because detection of the periostin protein levels may not correlate with the disease burden." (PMID 30911061, 2019). "In patients with non-small cell lung cancer (NSCLC) a positive immunostaining of Periostin in the mesenchymal areas, but not in the cancer cells themselves, could be demonstrated." (PMID 25221676, 2014). "Similar to periostin, CNN family members are induced by growth factors and cytokines, such as TGF-β and endothelin 1, and cellular stress, including hypoxia, and are overexpressed in pathological conditions that affect connective tissues, including scarring, fibrosis and cancer." (PMID 24273600, 2013). "Moreover, activation of several FGF downstream signaling pathways was also observed including cancer related pathways (RAS-MAPK, PIK3-AKT, and STAT) with a significant upregulation of several key molecules in these pathways (e.g., BIRC5, RAF1, MYCN, IGF2, SNAI2, POSTN)." (PMID 31477684, 2019). "Periostin (POSTN) and CTHRC1 are extracellular matrix (matricellular) proteins that contribute to progression in multiple human cancer types but have not been studied in MPNST." (PMID 39511408, 2025). "We confirmed expression of two additional upregulated gene candidates, POSTN and CTHRC1, that have not been previously assessed in human MPNST but are known contributors to progression in other human cancer types." (PMID 39511408, 2025). "We observed the overexpression of isoforms of genes C3orf17, FRMD4A, FZD6, HNRNPA2B1, POSTN, PRKAA1, RRBP1 and VEGFA, and the under expression of TRIP12 isoform (ENST00000428959) in ACC patients who are not free of cancer, which is a surrogate for poor ACC outcomes." (PMID 33035235, 2020). "While these observations support the potential therapeutic relevance of TW-POSTN signaling, the mechanisms by which TW may regulate POSTN expression in GBM and other cancers are not known." (PMID 31540485, 2019).
renal disease (18 papers, 2012 to 2025). "Periostin is rarely expressed in healthy tissues, but overexpressed in different renal lesions both in animal and human renal diseases, which is associated with the decreased renal function." (PMID 39570100, 2024). "The transcriptome sequencing data of humans obtained from the GEO revealed that FN1 and POSTN were both significantly associated with many different heart and kidney diseases." (PMID 35133974, 2022). "The indirect evidence partly demonstrated that FN1 and POSTN are strongly associated with many different heart and kidney diseases, thereby influencing the pathogenesis of CRS." (PMID 35133974, 2022). "Regression analyses found a strong association between periostin mRNA expression and robust functional markers of kidney disease." (PMID 22403621, 2012). "Subsequent studies have shown that periostin, in addition to being a marker, is an active player in the progression of kidney disease." (PMID 35883655, 2022). "Proteomic analysis revealed that TDC blocks periostin, which plays a crucial role in the progression of renal diseases through the regulation of TGF-β/Smad signaling." (PMID 34084130, 2021). "In the past few years, several studies have identified periostin as a new key player in the progression of kidney disease." (PMID 34084130, 2021). "Periostin expression levels in kidneys and urine are also highly correlated with pathological stage and renal function decline in patients with renal disease in different age groups." (PMID 34084130, 2021). "Recent studies have identified periostin as a novel key factor in the progression of kidney disease." (PMID 34768419, 2021). "Further studies demonstrated that both periostin and DDR1 are involved in the regulation of inflammation and fibrosis, two major processes implicated in the development of renal disease." (PMID 28536691, 2017). "In parallel, periostin was found de novo expressed in biopsies from patients with various renal diseases, including diabetes, lupus nephritis, IgA nephropathy, and focal segmental glomerulosclerosis." (PMID 28536691, 2017). "The results indicated periostin could participated in the development of RIF in DKD which might serve as a potential biomarker of renal disease progression." (PMID 39570100, 2024). "The vital roles of FN1 and POSTN in heart and kidney disease have previously been reported." (PMID 35133974, 2022). "Periostin is strongly up-regulated in several renal disease models and kidney biopsy specimens." (PMID 35883655, 2022). "By using experimental models of kidney diseases, periostin has been identified amongst the most represented matricellular proteins that are commonly involved in the inflammation and fibrosis that characterize progressive kidney diseases." (PMID 36551967, 2022). "There is limited information on the role of POSTN in kidney disease." (PMID 33488671, 2020). "In renal disease, periostin mediates the phosphorylation of FAK, p38, and Erk." (PMID 32102389, 2020). "It remains to be elucidated whether periostin may represent an earlier and more specific marker for renal disease or a subgroup of CKD patients compared to the existing standards." (PMID 28536691, 2017). "Using experimental models of renal disease, we identified and studied two promising candidates: periostin, a matricellular protein with high expression in bone and dental tissues, and discoidin domain receptor 1 (DDR1), a transmembrane collagen receptor of the tyrosine kinase family." (PMID 28536691, 2017). "Subsequent studies by our group investigated the role of periostin in renal disease." (PMID 28536691, 2017). "Its histopathologic expression patterns in the kidney in situ suggest that periostin participates in the pathogenesis of renal disease in response to transforming growth factor-beta (TGF-beta) and that blocking periostin expression protected animals from renal injury." (PMID 25884625, 2015).
renal disease (continued). "Periostin, initially found in epithelial cells and cystic fluid of the autosomal dominant polycystic kidney, could accelerate the proliferation of cystic wall epithelial cells and promote the remodeling of renal interstitial in renal disease." (PMID 39570100, 2024). "The level of periostin mRNA was positively correlated with blood creatinine and urine protein levels, and negatively correlated with renal blood flow, suggesting that periostin may have the potential to reflect the outcome, prognosis and efficacy prediction of renal disease." (PMID 33241962, 2020). "However, there has been no clinical research in this area, and further studies on the expressions of serum and urine periostin are needed to predict whether it can reflect the progress of the disease and predict its appropriate level when treating patients with kidney disease." (PMID 33241962, 2020). "In this context, both periostin and DDR1 may represent potential targets for therapy of renal disease." (PMID 28536691, 2017). "Among them, periostin showed the highest overexpression and since it was not reported before to be involved in renal disease, we investigated in subsequent studies more precisely its expression." (PMID 22403621, 2012). "Indeed, mice lacking periostin are protected against the development of kidney disease in several models of CKD." (PMID 35883655, 2022). "The urinary fraction of periostin seems to originate from the tubulointerstitium since serum periostin levels have not shown a reliable prognostic value in kidney disease and urinary periostin levels have not been significantly different between proteinuric and non-proteinuric conditions." (PMID 36551967, 2022). "Although these results suggest that periostin may serve as a new biomarker for the progression of renal disease, its role in the development of kidney disease is not fully clear." (PMID 34084130, 2021). "Besides, we also demonstrated that mice lacking periostin exhibit highly attenuated immune responses during development of renal disease." (PMID 28536691, 2017).
cardiovascular disease (11 papers, 2016 to 2024). "A correlation between ANRIL and POSTN has been found in an investigation of genetic risk for cardiovascular disease." (PMID 31572679, 2019). "Previous literature reviews support the potential pathological and physiological role of POSTN in cardiovascular disease." (PMID 38082393, 2023). "Recently, numerous studies have shown that POSTN plays an important role in cardiovascular disease." (PMID 35282347, 2022). "Furthermore, evidence of a recent review supports the potential role of periostin in the pathophysiology of cardiovascular diseases." (PMID 36010292, 2022). "Periostin is a 93-kDa secreted N-glycoprotein that mediates cell-matrix interactions and cell functions in the extracellular matrix and has been identified in many pathological conditions such as cardiovascular diseases, tumors, and airway inflammation." (PMID 36010292, 2022). "In inflammatory conditions including cardiovascular disease and ulcerative colitis ANRIL expression correlates with increased expression of three pro-inflammatory cytokines IL6, CCL2, and POSTN." (PMID 31572679, 2019).
infection (11 papers, 2016 to 2025). The state of being infected such as from the introduction of a foreign agent such as serum, vaccine, antigenic substance or organism. "The expression levels of POSTN were quantified by qPCR and western blotting 72 h after infection and screening." (PMID 33409280, 2020). "The observation that POSTN expression is significantly reduced in animals challenged with ∆potABCD suggests its requirement in establishing infection by WT TIGR4 in lungs." (PMID 27247105, 2016). "Periostin expression increased at 2 weeks post-infection (P < 0.0001) and maintained a higher expression at 4 weeks (P < 0.0001), 8 weeks (P = 0.0001) and 12 weeks (P = 0.0003) post-infection when compared to pre-infection." (PMID 41325491, 2025). "Additionally, genes related to cell adhesion such as ADGRF5, CAVIN2, FAT3, FILIP1, GSN, and TSPAN11 were downregulated in both the variants at 24hpi whereas CAV1, CAVIN1, GPC3, POSTN, SUSD2, and TSPAN7 were downregulated only after Delta variant infection at 24 hpi." (PMID 41200555, 2025). "Similarly, IL-5, IL-13, periostin (a marker of type-2 inflammation) and eotaxin-2 were not increased in RAGE deficient mice upon re-infection with PVM (p=0.8815, p>0.9999 and p>0.9999)." (PMID 28099113, 2017).
inflammation (10 papers, 2013 to 2025). Aberrant reaction of the microcirculation characterized by movement of fluid and leukocytes from the blood into extravascular tissues. "Previous findings have demonstrated the critical role of CCL26 and periostin in regulating eosinophilic inflammation." (PMID 39361432, 2024). "In particular, periostin is a major mediator of tissue remodeling under conditions of eosinophilic inflammation and in various inflammatory diseases." (PMID 36421442, 2022). "Periostin is secreted by bronchial epithelial cells and pulmonary fibroblasts and is recognized as a biomarker of type 2 eosinophilic inflammation." (PMID 33203095, 2020). "Serum periostin has been proposed as a systemic biomarker of eosinophilic inflammation." (PMID 27965769, 2016). "There was an abnormally high expression level of periostin in the NSCLC and lung chronic inflammation patients, and the periostin expression level was much higher in the male and non-ADC groups of NSCLC patients." (PMID 24273600, 2013). "In addition, WEIF and its components, DCQA, ABL, and 6-methoxyluteolin, contribute to the inhibitory effect of WEIF on the level of the type 2 inflammatory marker periostin by suppressing JAK2-STAT3/6 activation in human bronchial epithelial cells, which ameliorates OVA-induced airway inflammation." (PMID 40806199, 2025). "Moreover, serum TNC levels were associated with peripheral blood neutrophil counts in the especially periostin-high subgroup or IgE-high subgroup, suggesting that serum TNC levels may reflect not only type 2 airway inflammation but also neutrophilic airway inflammation." (PMID 30473714, 2018). "In contrast, TGF-β1-induced gene expressions of α-SMA and periostin were not blocked and was further exaggerated by dexamethasone, reflecting refractoriness to corticosteroids against TGF-β1-induced airway inflammation." (PMID 33579280, 2021).
respiratory disease (8 papers, 2018 to 2024). "Periostin is a matricellular protein and is a useful marker in respiratory diseases." (PMID 32517742, 2020).
metabolic disease (6 papers, 2016 to 2025). A congenital disorder (due to inherited enzyme abnormality) or acquired (due to failure of a metabolically important organ) disorder resulting from an abnormal metabolic process. "Thus, the associations between plasma periostin levels and metabolic disorders merit further investigation." (PMID 27313402, 2016). "The respective contribution of different tissues to circulating periostin and their involvement in the clinical manifestation of metabolic diseases remains to be clarified in further detail." (PMID 30088333, 2018). "Recent studies in both animal and human models show that periostin is involved in the pathophysiology of metabolic diseases." (PMID 27313402, 2016). "Recent studies also report a link between periostin and metabolic diseases via the JNK-mediated suppression of fatty acid oxidation in the liver." (PMID 27313402, 2016).
cardiac disease (5 papers, 2018 to 2025). "Nonetheless, our findings not only further support the potential of POSTN as a new cardiac disease biomarker but also validate the reliability of our previous proteomic results." (PMID 38082393, 2023). "Furthermore, the mediating role of POSTN in ECM crosstalk has received attention due to its correlation with fibroproliferative cardiac diseases." (PMID 39701940, 2024).
benign tumors (1 paper, 2025). "Semi-quantitative analysis of POSTN expression in the human TMA showed that similar proportions of malignant (73%; n = 16 of 22 cores) and benign tumors (75%; n = 15 of 20 cores) exhibited POSTN expression in at least 25% of the sample." (PMID 39511408, 2025).
bone cyst (1 paper, 2018). "Periostin was also seen in cellular fibrous tissue and areas of reactive osteoid/bone formation in other bone lesions, including simple bone cyst, ABC, fracture callus and myositis ossificans." (PMID 30202513, 2018).
connective tissue disease (1 paper, 2018). "IPA demonstrated the involvement of relevant genes (OPN, POSTN, MMP-1, MMP-7, Prominin-1, and others) in the network “connective tissue disease, organismal injury and abnormality”, and other functions related to cell movement and connective tissue disorder." (PMID 30111332, 2018).
musculoskeletal diseases (1 paper, 2023). "Therefore, POSTN-neutralizing antibodies are a therapeutic agent for spinal musculoskeletal diseases owing to their anti-aging properties." (PMID 38020106, 2023).